CDH1 (cadherin 1)
Diseases named in the same sentence as CDH1 in open-access papers (continued):
Sharing a sentence is not in itself a finding about the gene and the disease.
renal carcinoma (40 papers, 2009 to 2025). A carcinoma arising from the epithelium of the renal parenchyma or the renal pelvis. "Kidney carcinoma was the only tumor that showed lower E-cad staining compared to normal tissues, consistent with its CDH1 mRNA expression profile." (PMID 37189027, 2023). "The decreased levels of CDH1 mRNA in advanced stages coincide with the invasion of surrounding vessels and tissues, suggesting that the lower levels of CDH1 mRNA in kidney carcinoma are closely related to tumor invasion." (PMID 37189027, 2023). "When CDH1 was knocked down again using RNA interference, the renal carcinoma cells regained their migration capability." (PMID 36700046, 2022). "(2018) found that renal carcinoma cell lines transfected with CDH1 saRNA had a reduced migration capability compared with non-transfected cells, as measured using a Matrigel invasion chamber assay." (PMID 36700046, 2022). "In addition, CDH1 promoter methylation is significantly elevated in all stages of kidney carcinoma compared to normal samples." (PMID 37189027, 2023). "When kidney carcinoma was divided into four subtypes based on the differential expression of 500 genes and 500 microRNAs, CDH1 mRNA levels were significantly downregulated in cluster 2 (m2), cluster 3 (m3), and cluster 4 (m4), but remained unchanged in cluster 1 (m1) compared to normal tissues." (PMID 37189027, 2023). "Indeed, we found that the levels of CDH1 mRNA and E-cad protein were downregulated in certain carcinomas, particularly kidney carcinoma." (PMID 37189027, 2023). "Cell experiments confirmed the inhibitory effects of increased GJA1 expression on the migratory capacity of human renal cancer (RCC) cell lines, and protein–protein interaction (PPI) analysis predicted that CDH1 and CTNNB1 were closely related to Cx43." (PMID 38792963, 2024). "The exception was the kidney carcinoma lineage, in which the cell lines exhibited a weak correlation between CDH1 mRNA levels and E-cad protein levels." (PMID 37189027, 2023). "In addition, 10 out of the 14 examined kidney carcinoma cell lines (71.4%) exhibited low or no detection of CDH1 mRNA, and only 4 out of the 14 (28.6%) kidney carcinoma cell lines exhibited moderate to high levels of CDH1 mRNA." (PMID 37189027, 2023). "The same results were verified in renal cancer tissues, with a positive correlation between RBM47 and CDH1(e-cadherin), a negative correlation between RBM47 and TGF-β, snail, vimentin by qRT-PCR, and western blot (WB)." (PMID 37962768, 2023).
prostate tumor (37 papers, 2007 to 2025). "To directly assess the role of loss of E-cadherin in prostate tumor progression, we generated a new mouse model with bigenic Cdh1 and Pten deletion in prostate epithelium." (PMID 31658259, 2019). "This study found that RBM6 can promote the migration ability of prostate tumours through CDH1, and its expression is regulated by ZEB1 transcription." (PMID 39900560, 2025). "Our findings reveal that RBM6 promotes the migratory capacity of prostate tumours by inhibiting CDH1, and its activity is also regulated by the key transcription factor ZEB1 of the EMT pathway." (PMID 39900560, 2025). "Of note, increased CDH1 expression is associated with exit from EMT and growth of aggressive, metastatic prostate tumors." (PMID 33585078, 2021). "Our analysis shown that expression of CDH1 was actually reduced in prostate tumors from patients older than 50 years old." (PMID 29206234, 2017). "In human prostate tumors, expression of CDH1 is strongly reduced and its promoter is methylated to varying degrees." (PMID 22547956, 2011). "In advanced human prostate tumors, expressionof CDH1 is strongly reduced." (PMID 30825285, 2019). "CAV1 mediates the internalization of CDH1 and is up-regulated in prostate tumors." (PMID 22328933, 2012). "Therefore, we hypothesized that the promotion effect of RBM6 on the migration ability of prostate tumours may be played by CDH1." (PMID 39900560, 2025). "Next, we characterize at the molecular level prostate tumors at the time of biopsies evaluating, as novel prognostic biomarkers, eNOS, HIF-2α, and β4 integrin by immunohistochemistry (IHC) and, in parallel, H19 and CDH1 RNA levels by ddPCR." (PMID 39457633, 2024). "CDH1 is genetically inactivated in many human cancers and shows reduced or absent expression in approximately 50% of prostate tumors, playing a critical role in the transition from a noninvasive to an invasive phenotype." (PMID 18190704, 2008). "In particular, we found primarily overexpression of CTNNB1, CDH1, SMAD2, SMAD3, TCF3, LEF1 in younger patients and overexpression of SNAI1 and underexpression of KRT5, KRT19, OCLN, CDH2 and MUC1 which clearly indicates different characteristics of prostate tumor in younger vs older patients." (PMID 29206234, 2017).
colorectal tumors (35 papers, 1992 to 2025). "For example, we found that 3.5% of colorectal tumors and 1.9% of lung tumors had at least one CDH1 mutation." (PMID 29156750, 2017). "First, we found that patients homozygous for the rs9924886 minor allele had worse survival and second, we observed that patients with low CDH1 expression in their colorectal tumours had worse outcome." (PMID 38665548, 2023). "Here, we evaluated the prevalence of hypermethylation in the CDH1, CDKN2A, DAPK, and TIMP2 suppressor tumors genes of colorectal tumors tissue and their non-neoplastic adjacent margin using methylation specific PCR (MSP), which is a highly sensitive and specific technique." (PMID 26363785, 2015).
diabetes (35 papers, 2010 to 2025). "Nevertheless, we believe that our study has provided important information on the close association of long-term diabetes and the promoter methylation of CDH1 with unfavorable prognosis." (PMID 29273724, 2017). "In this study, we studied whether diabetes influences the clinico-pathological profile and methylation status of CDH1 and CDKN2A genes in patients with PDC." (PMID 29273724, 2017). "Likewise, some early connections of CDH1 (cell adhesion) and STK11 (metabolic LKB1 regulator) with type 2 diabetes mellitus establish common pathways for both diseases." (PMID 40989682, 2025). "Although we have not found transcriptional up-regulation of PFKFB3 in the “loser” HPAP datasets, we found that APC/Cdh1 E3 ubiquitin ligase that regulates PFKFB3 stability was down-regulated in T2DHPAP, in line with PFKFB3 protein up-regulation in diabetes." (PMID 39313296, 2024). "Compared to patients without diabetes, patients with T2D showed a decreased E-cadherin/N-cadherin (CDH1/CDH2) ratio in prostate tissue, indicating a switch of epithelial-mesenchymal transition (EMT), which is a pivotal process in carcinogenesis." (PMID 33207809, 2020). "It is of a particular note that frequency of methylation-positive cases for CDH1 was more common in PDC with long-DM than previously reported data in general PDC groups in which the presence of diabetes was not specified." (PMID 29273724, 2017). "Here we observed a decreased CDH1/CDH2 ratio in PCa samples of patients with T2D suggesting that EMT is induced in these samples, which may contribute to the more aggressive PCa phenotype of patients with diabetes." (PMID 33207809, 2020). "Since only a single PDC case with short-DM (1/17 cases, 6%) showed promoter methylation of CDH1 or none for CDKN2A in non-neoplastic tissues, it is likely that the presence of long-term diabetes may be a major trigger for the epigenetic alterations of tumor suppressor genes." (PMID 29273724, 2017). "Short disease duration without diabetes complications perhaps also helps to explain why the baseline elevations of PPBP, THBS1, and CDH1 were modest in this T2D population, though may additionally indicate that they are more sensitive markers of AIS due to LVO." (PMID 34926573, 2021). "In this study, we evaluated the methylation status of CDH1 and CDKN2A promoters in PDC tissues and non-neoplastic tissues obtained from patients with or without diabetes and explored to clarify whether diabetes influences tumor behavior and prognosis of the patients." (PMID 29273724, 2017).
cyst (33 papers, 2007 to 2025). A sac-like closed membranous structure that may be empty or contain fluid or amorphous material. "We also quantified migration patterns, cyst morphology, and matrix deformation rates for epithelial cysts where E-cadherin (CDH1), another classical cadherin, was depleted (CDH1-/-)." (PMID 41424915, 2025). "Immunofluorescence studies validated GPRC5A expression in CDH1 + cyst-lining cells (left), while its expression was faint in CDH1 + tubular cells in control kidneys (right)." (PMID 36310237, 2022). "At the umbrella stage (15 h), the cyst head broke through the shells with the tail remaining inside, at which point As-CDH1 expression was very high." (PMID 27991546, 2016). "We identified a GPRC5A + CDH1 + PC lineage (PKD-CDC1) in cyst-lining cells." (PMID 36310237, 2022). "Most cyst-lining cells expressed the distal nephron marker CDH1 in our samples." (PMID 36310237, 2022). "Whole mount immunohistochemistry of CDH1 showed low expression at 0 h (gastrula stage), thereafter the expression showed an increasing tendency from 5 h to 10 h throughout the cyst." (PMID 27991546, 2016). "In the case of TSC2−/− cell aggregates, the cystic structures stained positive for both the CDH1 and LTL, indicating the cyst-like structures could comprise distal tubule and/or proximal tubule cells." (PMID 34764250, 2021).
sarcoma (33 papers, 2004 to 2025). A usually aggressive malignant neoplasm of the soft tissue or bone. "Moreover, the expression of CDH1 (E-cadherin) decreased, and the expression of CDH2 (N-cadherin) and VIM (vimentin) increased in the dECM compared to 2D culture with plastic dishes and culture on Matrigel, which is a crude extract of the basement membrane formed by Engelbreth-Holm-Swarm sarcomas." (PMID 31013621, 2019).
pancreatic adenocarcinoma (31 papers, 2001 to 2025). "Survival analysis indicated that high expression of Cdh1 was associated with poor prognosis in patients with pancreatic adenocarcinoma." (PMID 38188879, 2023). "Kaplan–Meier survival analysis indicated that high Rela (Logrank p = 0.046), Actb (Logrank p = 0.038), Cdh1 (Logrank p = 0.041) and Vcl (Logrank p = 0.011) gene expression was associated with poor prognosis in patients with pancreatic adenocarcinoma." (PMID 38188879, 2023). "Finally, we assessed the expression of SQSTM1 and CDH1 in human pancreatic adenocarcinoma where 90% of tumors harbor KRAS mutations." (PMID 30782064, 2019). "Finally, accumulation of SQSTM1 protein correlates with loss of CDH1/E-cadherin expression in pancreatic adenocarcinoma." (PMID 30782064, 2019). "Similar to pancreatic adenocarcinoma where CDH1 (E-cadherin) is downregulated, GR activation in ILC may act as a complementary pathway to E-cadherin loss by upregulation of EMT gene expression and induction of a metastatic phenotype." (PMID 37835373, 2023).
neuroblastoma (26 papers, 2004 to 2025). Neuroblastoma (NB) is the most common solid, extracranial childhood tumor. "This pilot study validates that ML327 is capable of inducing CDH1 expression within neuroblastoma xenografts and demonstrates conservation of the gene signature changes observed in vitro." (PMID 29207623, 2017). "ML327 induced the expression of CDH1 in all seven of the neuroblastoma cell lines with a 50 to 1,400-fold induction of CDH1 mRNA expression." (PMID 29207623, 2017). "In the present study, it was suggested that the mRNA and protein levels of CDH1 decreased in metastatic neuroblastoma (NB) tissues compared with those in primary NB tissues." (PMID 24520301, 2014). "Although SNAIL and CDH1 were not identified in our RNAseq analysis, it is possible that TFAP4 regulates a different set of EMT effectors and may restrict differentiation of MYCN-amplified neuroblastoma by this mechanism as well." (PMID 29880876, 2018).
signet ring cell carcinoma (26 papers, 2011 to 2025). A usually aggressive, poorly differentiated invasive adenocarcinoma characterized by the presence of malignant glandular cells in which the nucleus is pressed to one side by the presence of intracytoplasmic mucus. "For CDH1-mutation carriers, when signet-ring cell carcinoma or diffuse GC is confirmed via gastroscopy, radical total gastrectomy, and perioperative treatment are recommended according to the disease stage." (PMID 41378303, 2025). "More than 90% of individuals with germline pathogenic CDH1 variants will harbor occult, microscopic foci of signet ring cell carcinomas capable of progressing to advanced diffuse-type gastric cancer." (PMID 37925632, 2023). "In a relatively large surveillance study on 54 CDH1-mutated patients (and 31 CDH1−), 36 patients were diagnosed with signet ring carcinoma including 15 that had positive histological findings from targeted biopsy sampling." (PMID 35499650, 2023). "And due to the poor sensitivity of gastroscopy for the detection of signet ring cell carcinoma, the monitoring of CDH1 mutation patients is very limited." (PMID 34422902, 2021). "Morphologically, it resembles signet ring cell carcinoma of the stomach and breast, raising the possibility of mutations in CDH1, the gene encoding E-cadherin." (PMID 33617508, 2021). "One of the articles showed almost 64% of the signet ring cell carcinoma (SRCC) were found to be positive with CDH1 mutation." (PMID 33062523, 2020). "In summary, we present the first case report of an appendiceal signet ring cell carcinoma in an individual with synchronous CDH1-associated hereditary diffuse gastric carcinoma." (PMID 23849133, 2013). "Herein we describe the first reported case of primary appendiceal signet ring cell carcinoma arising in a CDH1-associated hereditary diffuse gastric carcinoma kindred with synchronous primary diffuse gastric carcinoma." (PMID 23849133, 2013). "Herein we describe a case of primary appendiceal signet ring cell carcinoma arising in a 51 year old female from a CDH1-associated HDGC kindred who underwent an interval appendectomy at the time of a prophylactic gastrectomy." (PMID 23849133, 2013). "The prophylactic gastrectomy specimen of our patient known to carry a CDH1 mutation was found to have multifocal intramucosal signet ring cell adenocarcinoma despite normal endoscopic exam and biopsies." (PMID 21331337, 2011). "CDH1 knockout mice (C57BL/6 background) have been generated, and in the MNU carcinogenesis model, CDH1+/− mice developed signet ring cell carcinoma with a high tumor incidence rate." (PMID 24216700, 2013). "This mixture has similarities to the stomachs of germline CDH1 mutation carriers, whereby discrete regions of E-cadherin-negative gastric cells result in signet ring cell carcinoma formation in a greater milieu of E-cadherin-positive cells." (PMID 31540244, 2019). "Studies in a CDH1 knock-out animal model showed that parietal cells can “float” in the lamina propria, mimicking signet ring cell carcinoma, suggesting that parietal cells are possible cell of origin for signet ring cell carcinoma." (PMID 30568591, 2018). "This study aimed to determine the yield of signet ring cell carcinoma (SRCC) foci in individuals with a CDH1 pathogenic variant compared with those without and how this varies with successive endoscopies." (PMID 28688938, 2018). "Of reported cases, only one has been diagnosed as a signet ring cell carcinoma; there is at least one additional case of a colonic signet ring cell carcinoma occurring in a family with familial gastric carcinoma that tested negative for the CDH1 mutation (and negative for HNPCC)." (PMID 23849133, 2013). "Conditional knockout of CDH1 in mouse stomach induces signet ring–like cells in stroma (analogous to intramucosal signet ring cell carcinoma) but not the development of carcinoma invading into submucosa." (PMID 30568591, 2018).
signet ring cell carcinoma (continued). "A recent study examining 20 carriers of CDH1 germline mutations who did not fulfill family history criteria for HDGC reported that while none had suspicious diagnostic findings on conventional endoscopy, 12 showed signet ring carcinoma cells on histology of gastrectomy specimens or random biopsies." (PMID 35499650, 2023). "In addition, CDH1 testing could be considered in patients with bilateral or familial LBC before the age of 50, patients with DGC and cleft lip/palate, and those with precursor lesions for signet ring cell carcinoma." (PMID 33797633, 2021).
clear cell renal cell carcinoma (25 papers, 2008 to 2025). "Interestingly, we found that RASSF10 expression is positively associated with increased CDH1 levels in renal clear cell carcinoma (p = 4.6 × 10−9)." (PMID 32047266, 2020). "We aimed to determine prognostic value of six key EMT markers (CDH1, CDH2, SNAI1, SNAI2, VIM, TWIST1) in clear cell renal cell carcinoma (ccRCC)." (PMID 31915310, 2020).
colon adenocarcinoma (25 papers, 2004 to 2024). "Moreover, only one meta-analysis showed that coffee polyphenols, caffeic acid and chlorogenic acid increased the MYO9B, PTPN11 and CDH1 gene expressions in un-stimulated colon adenocarcinoma HT29 cells." (PMID 33806347, 2021).
colorectal adenocarcinoma (24 papers, 2004 to 2025). The most common type of colorectal carcinoma. "In this study, we demonstrate that SARS-CoV-2 infection of non/low-mucus producing human colorectal adenocarcinoma Caco-2 cells results in the modulation of the CDH1 gene encoding the E-cad adhesion molecule as well as several other genes, including the gene encoding the virus receptor, ACE2." (PMID 35601094, 2022).
urothelial carcinoma (24 papers, 2003 to 2026). A malignant neoplasm derived from the transitional epithelium of the urinary tract (urinary bladder, ureter, urethra, or renal pelvis). "Using two oncogenes and the epithelium-specific promoters KRT14 and Cdh1 resulted in the most frequent growth of orthotopic urothelial carcinoma of all experimental groups." (PMID 39463382, 2024). "To further explore the mechanism of CDH1 underlying BC tumorigenesis, we investigated the correlated genes of CDH1 in urothelial carcinoma cells and their potentially enriched functions." (PMID 36131343, 2022). "CDH1 (E-cadherin) is involved in the inactivation of Wnt/β-catenin signalling in urothelial carcinoma and normal urothelial cells." (PMID 27534621, 2016).
metastasis (23 papers, 2002 to 2025). The spread or migration of cancer cells from one part of the body (where they first appeared) to another. "The results showed that GBC tissues from patients with liver metastasis had higher DNMT3A and YAP expression but lower CDH1 expression than those from patients without liver metastasis." (PMID 38380551, 2024).
inflammatory breast carcinoma (22 papers, 2003 to 2026). An advanced, invasive breast adenocarcinoma characterized by the presence of distinct changes in the overlying skin. "Although most data support the notion that CDH1 is a tumor suppressor, Kleer and coworkers have shown that in inflammatory breast cancers, E-cadherin seems to exert an opposite role." (PMID 34944948, 2021).